ARK2C (arkadia (RNF111) C-terminal like ring finger ubiquitin ligase 2C)
Description:
E3 ubiquitin-protein ligase that acts as a regulator of motor axon elongation. Required for efficient motor axon extension in the dorsal forelimb by enhancing the transcriptional responses of the SMAD1/SMAD5/SMAD8 effectors, which are activated downstream of BMP. Acts by mediating ubiquitination and degradation of SMAD inhibitors such as SMAD6, SMAD7, SKI and SNON isoform of SKIL.
Synonyms: RNF165; ARKL2; RNF111L2; lncAMPC
Tractability: Antibody: the Human Protein Atlas places it where antibodies can reach.
Gene: Protein-coding gene on chromosome 18 (46,326,809 to 46,463,140, forward strand). Ensembl gene ENSG00000141622.
Subcellular location: Nucleus
Subcellular location (Human Protein Atlas): Nucleoplasm; Plasma membrane
Gene Ontology:
Molecular function: protein binding; ubiquitin protein ligase activity; zinc ion binding
Biological process: motor neuron axon guidance; positive regulation of BMP signaling pathway
Cellular component: nucleus; protein-containing complex
Genetic constraint (gnomAD): Loss-of-function variants: 12 observed, 38.99 expected, observed/expected ratio (o/e) 0.31, 90% interval 0.2 to 0.5. The upper end of that interval is the gene's LOEUF score, 0.5, which puts it in group 2 of 6, group 1 being the genes least tolerant of losing a copy. Missense variants: 301 observed, 421.48 expected, observed/expected ratio (o/e) 0.71, 90% interval 0.65 to 0.79. Synonymous variants: 177 observed, 170.86 expected, observed/expected ratio (o/e) 1.04, 90% interval 0.92 to 1.17.
Homologues: Orthologues: chimpanzee ARK2C (100% identical), macaque ARK2C (100% identical), mouse Ark2c (99% identical), pig ARK2C (99% identical), rat Ark2c (99% identical), guinea pig ARK2C (95% identical), rabbit ARK2C (94% identical), dog ARK2C (90% identical), tropical clawed frog ark2c (85% identical), zebrafish ark2cb (70% identical), zebrafish ark2ca (66% identical), Drosophila melanogaster CG6923 (23% identical), and 1 more. Paralogues in human: RNF111 (48% identical), ARK2N (8% identical).
Diseases named in the same sentence as ARK2C in open-access papers:
ARK2C is named in the same sentence as 12 diseases in open-access papers, as found by Europe PMC text mining. Sharing a sentence is not in itself a finding about the gene and the disease.
ARK2C shares sentences with these, for which no sentence is quoted: aleutian mink disease (1 paper); amyotrophic lateral sclerosis (1); attention deficit-hyperactivity disorder (1); autism spectrum disorder (1); bipolar disorder (1); cancer (1); eating disorder (1); infection (1); major depressive disorder (1); mental disorder (1); schizophrenia (1); viral infection (1).